ENSG00000269026 (novel protein)
Gene: Protein-coding gene on chromosome 19 (57,682,045 to 57,753,575, forward strand). Ensembl gene ENSG00000269026.
Genetic constraint (gnomAD): Loss-of-function variants: 5 observed, 7.48 expected, observed/expected ratio (o/e) 0.67, 90% interval 0.35 to 1.39. That is too few expected variants to judge how well the gene tolerates losing a copy. Missense variants: 161 observed, 183.76 expected, observed/expected ratio (o/e) 0.88, 90% interval 0.77 to 1. Synonymous variants: 77 observed, 65.58 expected, observed/expected ratio (o/e) 1.17, 90% interval 0.98 to 1.42.